NQO1 (NAD(P)H quinone dehydrogenase 1)
Diseases named in the same sentence as NQO1 in open-access papers (continued):
Sharing a sentence is not in itself a finding about the gene and the disease.
tumor (continued). "Such a differentiated expression mode of NQO1 between tumors and normal tissues suggests that NQO1 target drugs would be highly selective in killing tumor cells while saving normal tissues." (PMID 22848731, 2012). "Although some anti-tumor drugs such as mitomycin can be bioactivated by NQO1, all of them lack sufficient selectivity and specificity to NQO1 and their anti-tumor effects are better explained by other mechanisms." (PMID 22848731, 2012). "Evidence collected from the studies of Lap indicates that the NQO1 activated futile redox cycle can induce a unique cell death pathway, inspiring the new idea of developing NQO1 target anti-tumor drugs." (PMID 22848731, 2012). "Many tumor cells have endogenous overexpression of NQO1, which explains the chemotherapeutic effectiveness of the drug." (PMID 21912624, 2011). "Insight gained in the present study on the molecular signaling pathway in β-lap-induced cell death will lead to advances in establishing the strategies for NQO1-targeted tumor treatment." (PMID 21738692, 2011). "In summary this study has demonstrated that functional groups of different steric size can be used to produce a series of bioreductive antitumor agents that are activated by different levels of NQO1 in tumor cells." (PMID 21904446, 2009). "In the FaDu cells with the highest NQO1 activity, the relative tumor cell growth inhibitory activity was p-MeBM > m-MeBM = p-PBM > m-nPrBM = m-PBM." (PMID 21904446, 2009). "NQO1 activity varies in individual tumors but is generally higher in tumor cells than in normal cells." (PMID 21904446, 2009). "We compared the tumor cell growth inhibitory activity of benzoquinone mustard analogs with sterically bulky groups of different size and placed at different positions on the benzoquinone ring, using tumor cell lines with different levels of NQO1." (PMID 21904446, 2009). "The level of induction of NQO1 in the tumours was similar to that observed previously in vitro, and the lack of enzyme induction in the bone marrow was important as marrow toxicity is the dose-limiting toxicity for MMC in the clinic." (PMID 15467770, 2004). "We used a novel approach to increase MMC efficacy by selectively inducing NQO1 in tumour cells in vivo." (PMID 15467770, 2004). "NQO1 activity was increased 2.5-fold in the tumours of mice fed a diet containing 0.3% DMF compared with mice fed control diet; however, there were similar increases in NQO1 activity in the kidneys and forestomachs of the inducer fed mice." (PMID 15467770, 2004). "We have previously shown that NQO1 activity can be selectively increased in tumour cells compared with normal cells, and that this enhances MMC cytotoxicity in human and murine cell lines in vitro." (PMID 15467770, 2004). "In this study we investigated a novel approach to increasing the antitumour activity of MMC by using a dietary component to selectively induce NQO1 activity in tumour cells compared with normal cells." (PMID 15467770, 2004). "We also found that NQO1 activity in HCT116 tumours implanted in CD-1 nude mice reached a plateau after 7 days on the DMF diet while enzyme activities in other tissues including kidney, liver, lung and forestomach showed a further increase at 14 days." (PMID 15467770, 2004). "We used DMF, a metabolite of fumaric acid that is found in fruits and vegetables, as the inducer of NQO1 and HCT116 cells, which have a moderate level of NQO1 activity, as a tumour model." (PMID 15467770, 2004). "Additional western blot analyses revealed that hexokinase II and phosphofructokinase-1 protein levels decreased in tumor tissues from the NQO1 knockdown group and increased in those from the overexpression group; these results were substantiated via IHC staining." (PMID 39939940, 2025).
tumor (continued). "Interestingly, sample 1081 exhibited high NQO1 activity in both tumour tissue and patient‐derived cells (PDCs), with RNA‐seq data showing the highest NQO1 mRNA levels among PDCs." (PMID 39707614, 2025). "It is hypothesized that IKE and DIC might induce ferroptosis and modulate other biological processes by regulating SLC7A11 and NQO1 expression, potentially explaining the observed reduction in tumor volume in our experiment." (PMID 40007539, 2025). "DDANQ exhibited the excellent NQO1 specificity and imaging capability, was used as a practical molecular tool to study the physiological function of NQO1 and is expected to be a clinical fluorescence-guided tumor resection reagent." (PMID 40630553, 2025). "NQO1 influences the progression of CNS tumors by affecting downstream signaling pathways, such as those involving the transcription factor SNAIL, as well as others that are associated with tumor behavior." (PMID 40002465, 2025). "Triggering ferroptosis via NQO1 can also combat tumor drug resistance." (PMID 40007539, 2025). "This indicates that Plerixafor effectively inhibited the tumor progression promoted by NQO1." (PMID 41028931, 2025). "Several studies indicate that tumor cells may enhance aerobic glycolysis and energy production for cell growth via modulating NQO1 expression." (PMID 39939940, 2025). "Furthermore, NQO1 mRNA levels were elevated in PBMCs, while reductions in NF-κB and cyclin D1 expression were observed in tumor samples." (PMID 40732256, 2025). "Recent evidence suggests that NQO1 may play roles beyond detoxification, influencing tumor biology and treatment response." (PMID 41010895, 2025). "In vehicle‐treated PDXs, NQO1 immunoreactivity was more evenly distributed among tumor cells." (PMID 40600748, 2025). "DDANQ could be used as a molecular tool to elucidate the activity and function of NQO1 in physiological and pathological processes, which could provide valuable insights for tumor diagnosis and treatment." (PMID 40630553, 2025). "Correlation of NQO1 expression with the clinico‐pathological features of pRCC showed that patients with NQO1‐positive tumours had a worse survival compared to those with NQO1‐negative tumours (p = .016)." (PMID 39707614, 2025). "NQO1 knockdown in human CRC cell lines suppresses tumor growth." (PMID 40205952, 2025). "This indicates that Plerixafor may regulate the TME and inhibit tumor progression by suppressing NQO1‐mediated Treg cell infiltration." (PMID 41028931, 2025). "Suppressing STEAP4 via knockdown techniques effectively attenuated the nuclear factor erythroid 2-related factor 2 (NRF2)–NAD(P)H:quinone oxidoreductase 1 (NQO1) signaling pathway, inducing apoptosis and autophagy, leading to substantial reductions in xenograft tumor growth." (PMID 40205952, 2025). "Besides, Nrf2 regulates ferroptosis in tumor cells by inducing the expression of NQO1, HMOX1, and FTH1." (PMID 40530331, 2025). "Upon X-ray irradiation, the upregulation of ROS and NAD (P) H: quinone oxidoreductase-1 (NQO1) in tumor cells accurately triggers β-Lap/Fe NPs to persistently generate high levels H2O2 and •OH for 12 hours, ultimately causing strong immunogenic cell death effects." (PMID 40585976, 2025). "Notably, five tumour tissue samples with high NQO1 mRNA levels showed NQO1 activation, which was confirmed in the corresponding PDC." (PMID 39707614, 2025). "Also, SN-38 in this setting was tumor-selective, influenced dually by the extent of biotin receptor distribution and NQO1 abundance." (PMID 39120303, 2024). "This phenomenon suggests that the highly expressed TRIB3 and NQO1 in blood-derived exosomes may originate from this particular subpopulation of highly stem-like HCC tumor cells." (PMID 39044829, 2024). "In addition, our laboratory has obtained evidence for immunogenic cell death (ICD) after cell tumor cell exposure to NQO1 futile substrates." (PMID 39120303, 2024).
tumor (continued). "In tumor cells rich in NQO1, the near-infrared fluorescence and cytotoxic properties of NCyNH2 were reactivated, thereby triggering pyroptosis by accumulating within acitve mitochondria, which successively caused mitochondrial membrane damage, cytochrome C release and caspase-3 activation." (PMID 39221221, 2024). "It has been widely described that Nrf2 overexpression in different tumor types contributes to pro-oncogenic processes and chemoresistance by promoting the transcription of antioxidant (NQO1), detoxifying (SULT1A1), and anti-apoptotic (BCL-2) enzymes with ARE element." (PMID 39034849, 2024). "Both NQO1-dependent and -independent cytotoxicity in tumor cell lines have been observed for RH1." (PMID 39120303, 2024). "Because the knockout of NQO1 in the A549 cells inhibited cell proliferation in vitro, the inoculation of 1 × 106 A549 cell or 1.3 × 106 A549-NQO1-KO cells resulted in similar rates of tumor growth in vivo." (PMID 38136388, 2023). "Furthermore, NQO1 expression was also closely related to tumor progression, aggressiveness, resistance to chemotherapy, and poor patient outcomes." (PMID 37583897, 2023). "We also analyzed the relationship between the NQO1 mRNA expression levels and the tumor subtypes." (PMID 37583897, 2023). "Tumors have different levels of NQO1 compared to normal tissue, and compounds containing NQO1-activated quinone pharmacophore should have significant tumor selectivity, which may lead to the development of NQO1-directed antitumor agents." (PMID 37583897, 2023). "Interestingly, when NQO1 expression was rescued in these knockdown cell lines, tumor spheroid formation was restored." (PMID 36980879, 2023). "Additionally, significant decreases in the formation of serial spheroids in both the A549 and H358 NSCLC cell lines suggest that NQO1 plays a supportive role in perpetuating the population of tumor-initiating cells." (PMID 36980879, 2023). "The biological analysis also demonstrated that NQO1, as a tumor promoter, could enhance tumor proliferation and metastasis and induce drug resistance to chemotherapy." (PMID 37188198, 2023). "Finally, RT-qPCR and Western blotting verified the profoundly higher expression of NQO1 in tumor Huh7.5 cells than is seen in non-tumor HepaRG or PHH cells." (PMID 37189460, 2023). "In contrast, the rescue of NQO1 expression restored the tumor cells’ ability to form spheroids." (PMID 36980879, 2023). "Hence, we also performed a cluster analysis using single-cell RNA sequencing to assess the role of NQO1 expression on the tumor immune microenvironment in depth." (PMID 37583897, 2023). "However, the NQO1 mRNA expression levels in our study varied between the same tumor types with different molecular phenotypes, pathological stages, or mutation types." (PMID 37583897, 2023). "NQO1 expression was significantly correlated with tumor purity (p = 2.25e-03)." (PMID 36686655, 2022). "NAD(P)H quinone oxidoreductase (NQO1), a cytoplasmic enzyme that mediates the reduction of quinone substrates, is highly expressed in a multitude of tumors and can catalyze quinone drugs to poison tumor cells." (PMID 35449571, 2022). "Finally, we demonstrated that osthole inhibited tumor growth and the expression of NQO1 in a HeLa xenograft mode." (PMID 35720178, 2022). "Subsequently, neither NQO1 rs1800566 polymorphisms nor any other NQO1 polymorphisms were found to be substantially linked with tumor risk in the genetic model." (PMID 36338728, 2022). "Of these, HS6ST2, COL10A1, and NQO1 were significantly up regulated in tumor tissues." (PMID 35260044, 2022). "Therefore, the potential target FRGs, SLC1A5, CD44 and NQO1, for tumor resistance treatment have important research value in the treatment of SCC drug resistance." (PMID 35501667, 2022).
tumor (continued). "Overall, the NRF2/NQO1 pathway is important in response to environmental toxins and may be a tumor suppressor." (PMID 35805773, 2022). "The abnormally upregulated NQO1 expression in 4T1 tumor cells was also confirmed using western blot assay, which was 8-fold higher than the healthy HC11 mouse mammary epithelial cells, suggesting the intrinsic tumor specificity of the nanoassembly-mediated chemotherapy." (PMID 36167857, 2022). "Furthermore, HOXA11-AS knockdown and HOXA11-AS knockdown + NQO2 inhibition reduced the sphere-forming ability of the cells, but this tumor characteristic was only slightly diminished by NQO1 inhibition." (PMID 36142607, 2022). "mIF enabled the quantitative assessment of NQO1 expression within tumor and TME regions." (PMID 36359002, 2022). "Notably, NQO1 protein expression was significantly higher in normal bronchial epithelial cells than in tumor cells across paired samples." (PMID 36359002, 2022). "In conclusion, under the protective effects of cellular immune surveillance, NQO1 homeostasis and iron homeostasis, most damaged cells undergo natural apoptosis or necrosis, but those “super tumor cells” must be cleared in time through reasonable treatments to avoid deterioration and metastasis." (PMID 35501667, 2022). "Ola and Lapa molecules delivered intracellularly by ZIF67/Ola/Lapa could synergistically achieve the tumor-specific sustainable ·OH production through NQO1-dependent futile redox cycling." (PMID 34481495, 2021). "In addition, we demonstrated that the NQO1 substrate dunnione attenuated pulmonary thrombosis in 4T1 tumor-bearing mice through the regulation of intracellular NAD+ levels." (PMID 34769515, 2021). "Nevertheless, we also cannot exclude the possibility that other factors directly or indirectly related to tumor development may have elevated the baseline level of Nqo-1 and Aldh1a3 in BMDMs." (PMID 34711804, 2021). "The reason for this specificity remains unclear and tumor-type specific roles of NQO1 could be one possible explanation." (PMID 33406703, 2021). "The released VK3 could produce abundant ROS selectively in tumor cells catalyzed by the overexpressed NAD(P)H: quinone oxidoreductase-1 (NQO1) enzyme." (PMID 34747277, 2021). "However, other cellular subcompartments, such as organellar and plasma membranes, deserve more thorough scrutiny, especially in regard to the presence of NQO1 upon its massive upregulation during oxidative stress and in some tumor types." (PMID 33406703, 2021). "It is interesting to note that some tumor types show constitutively elevated NQO1 protein levels." (PMID 33406703, 2021). "To this end, we examined whether the methylation of Nqo-1 and Aldh1a3 in BMDMs can be induced by a tumor-conditioned medium (TCM)." (PMID 34711804, 2021). "In this study, a new kind of enzyme-responsive combination quinone/quinone oxidoreductase 1 (NQO1) was introduced and utilized for the design of enzyme-triggered drug delivery system, because overexpression of NQO1 in several human tumor cells has been demonstrated." (PMID 32850662, 2020). "Since most solid tumors overexpress NQO1, combining low-dose radiation with a sublethal concentration of β-lap may enhance tumor-selective and targeted killing and improve patient safety by lowering the overall doses of both agents." (PMID 32974194, 2020).
tumor (continued). "Concerning the potential application of β-lap as anti-tumor treatment, it should be considered that also normal tissue cells which contain substantial NQO1 activity, such as brain astrocytes, may be affected by β-lap-induced oxidative stress." (PMID 32789798, 2020). "In addition, 10 (67%) out of 15 patients with low levels of NQO1 had advanced tumor (pathological stage pT3-4) while 7 (70%) of 10 in high NQO1 group had organ confined tumor (pathological stage pT2)." (PMID 31909204, 2020). "Overall, combining low-dose radiation therapy with NQO1-bioactivatable drugs may be a viable, less toxic, and more tumor-selective strategy for treatment of various solid tumors that overexpress a predictive biomarker, NQO1." (PMID 32974194, 2020). "Synergy occurred regardless of oncogenic and tumor-repressor mutations and was entirely NQO1-dependent in all cell types, according to the gold standard combinatorial index obtained using the Chou and Talalay method." (PMID 32974194, 2020). "Similarly, the antitumor effect of β-lap in NQO1-overexpressing B16 tumor models was also abolished in Myd88−/− mice or Ifnαr−/− mice." (PMID 31324798, 2019). "Here we screen and identify high NQO1 expression in murine tumor lines." (PMID 31324798, 2019). "Indeed, β-lap induced high level of ROS in NQO1-positive murine tumor lines and much less in NQO1-null lines." (PMID 31324798, 2019). "In this study, we demonstrate the tumor suppressive function of NQO1 in cutaneous SCC cells." (PMID 31886179, 2019). "MG132 treatment blocked tumor growth inhibition induced by NQO1 knock out." (PMID 31842909, 2019). "Through tumor specific NAD(P)H: NQO1 catalysis, La can generate massive H2O2." (PMID 30886808, 2019). "In this study, we demonstrated the tumor suppressive function of NQO1 in cutaneous SCC cells." (PMID 31886179, 2019). "As the invasive growth and migration are the important manifestations of tumor progression, we next investigated whether NQO1 affected those characteristics of SCC cells." (PMID 31886179, 2019). "Currently, we found that β-lap-induced NQO1+ tumor regression largely depends on host CD8+ T cells." (PMID 31324798, 2019). "In summary, we demonstrate that NQO1 has tumor suppressive function in cutaneous SCC cells." (PMID 31886179, 2019). "Based on these data, NQO1 has tumor suppressive function in cutaneous SCC cells." (PMID 31886179, 2019). "We successfully determined tumour NQO1 expression by IHC in all enrolled cases." (PMID 30318513, 2018). "A total of 78 patients had tumour tissue successfully tested for NQO1 expression." (PMID 30318513, 2018). "There was a trend towards improved efficacy in NQO1-high tumours (P = 0.06)." (PMID 30318513, 2018). "Four-month PFS rate was 26% in NQO1-high tumours vs. 13% in NQO1-low tumours (P = 0.3)." (PMID 30318513, 2018). "Consequently, accumulation of Nrf2 leads to aberrant activation of ARE-driven cytoprotective genes (e.g., HO-1, GCLM, NQO1) in so much as to shelter or promote Nrf1α−/−-driven tumor cells." (PMID 30562963, 2018). "Importantly, we also show here that NQO1 has significant prognostic value as a biomarker for the prediction of tumor recurrence." (PMID 28411284, 2017). "Notably, NAD+-SIRT1-FOXO1 pathway was found also disrupted in A549 tumor xenografts treated with NQO1 substrates." (PMID 27566573, 2016).